SLC9B1 (solute carrier family 9 member B1)
Description:
Sperm-specific Na(+)/H(+) exchanger involved in intracellular pH regulation of spermatozoa. Involved in sperm motility and fertility.
Synonyms: NHA1; NHEDC1
Tractability: Antibody: its Gene Ontology location is reachable by antibodies, with high confidence; UniProt predicts a signal peptide or a membrane-spanning region. PROTAC: it is named in the literature on targeted protein degradation.
Gene: Protein-coding gene on chromosome 4 (102,885,048 to 103,019,719, reverse strand). Ensembl gene ENSG00000164037.
Subcellular location: Cell projection, cilium, flagellum membrane
Subcellular location (Human Protein Atlas): Acrosome; Cytosol; Principal piece
Pathways (Reactome):
Transport of small molecules: Stimuli-sensing channels
Gene Ontology:
Molecular function: sodium:proton antiporter activity; antiporter activity
Biological process: flagellated sperm motility; monoatomic ion transmembrane transport; regulation of intracellular pH; transmembrane transport; monoatomic cation transport; proton transmembrane transport; sodium ion transmembrane transport
Cellular component: cytosol; plasma membrane; sperm principal piece; membrane
Genetic constraint (gnomAD): Loss-of-function variants: 10 observed, 16.96 expected, observed/expected ratio (o/e) 0.59, 90% interval 0.36 to 1. The synonymous counts are far from expectation, so gnomAD's model fits this gene poorly and the ratio says little. Missense variants: 214 observed, 323.76 expected, observed/expected ratio (o/e) 0.66, 90% interval 0.59 to 0.74. Synonymous variants: 78 observed, 110.29 expected, observed/expected ratio (o/e) 0.71, 90% interval 0.59 to 0.85.
Homologues: Orthologues: chimpanzee SLC9B1 (99% identical), macaque SLC9B1 (92% identical), rabbit SLC9B1 (74% identical), dog SLC9B1 (71% identical), pig SLC9B1 (68% identical), guinea pig SLC9B1 (66% identical), mouse Slc9b1 (66% identical), rat Slc9b1 (64% identical), tropical clawed frog slc9b2 (52% identical), zebrafish SLC9B2 (47% identical), Drosophila melanogaster Nha1 (35% identical), Drosophila melanogaster Nha2 (29% identical), and 3 more. Paralogues in human: SLC9B2 (55% identical).
Diseases named in the same sentence as SLC9B1 in open-access papers:
SLC9B1 is named in the same sentence as 18 diseases in open-access papers, as found by Europe PMC text mining. Sharing a sentence is not in itself a finding about the gene and the disease. The quoted sentences say what the papers report.
infertile (4 papers, 2016 to 2023). "We also find Slc9b1-KO males are infertile and feature a significantly reduced number of motile sperm." (PMID 32984353, 2020). "Additionally, genetic analysis in humans suggested disturbed SLC9B1 expression in men with infertility due to teratozoospermia." (PMID 35694410, 2022).
diabetes (2 papers, 2021 to 2026). "We found multiple genomic variants in GSTCD, SKAP2, SLC9B1 and BANK1 genes to be present at a relatively higher frequency in our patient cohort indicating a causal connection between these variants and the incidence of type 1 diabetes mellitus in Qatar." (PMID 34556755, 2021).
autoimmune disease (1 paper, 2021). A disorder resulting from loss of function or tissue destruction of an organ or multiple organs, arising from humoral or cellular immune responses of the individual to their own tissue constituents. "Interestingly, the lead SNP at the MANBA/UBE2D3 locus, rs223486, is an intergenic variant located in a region (±500 kb) that harbors several other genes (CISD2, NFKB1, SLC9B1/2, BDH2 and CENPE) with reported inflammatory and autoimmune disease associations." (PMID 33402679, 2021).
thyroid carcinomas (1 paper, 2021). "According to the COSMIC database, 14 thyroid carcinomas with SLC9B1 mutations are reported out of 1040 cases tested; 1.35%)." (PMID 33827048, 2021).
cancer (1 paper, 2022). A tumor composed of atypical neoplastic, often pleomorphic cells that invade other tissues. "The role of the SLC9B1 and ZNF624 proteins on cancer is completely unknown, so the downregulation of their mutant protein isoforms and the prediction of their benign impact do not allow conclusions to be drawn." (PMID 35454907, 2022).
tumor (1 paper, 2021). "Moreover, we found two somatic mutations in the SLC9B1 gene that were both present in the primary tumor as well as in the corresponding metastasis." (PMID 33827048, 2021).
SLC9B1 also shares sentences with these, for which no sentence is quoted: male infertility (3 papers); Alzheimer disease (1); amyotrophic lateral sclerosis (1); Arrhythmia (1); asthenozoospermia (1); essential hypertension (1); hyperglycaemia (1); infection (1); migraine (1); potassium deficiency (1); teratozoospermia (1); type 1 diabetes mellitus (1).